IFI16 (interferon gamma inducible protein 16)
Description:
Binds double-stranded DNA. Binds preferentially to supercoiled DNA and cruciform DNA structures. Seems to be involved in transcriptional regulation. May function as a transcriptional repressor. Could have a role in the regulation of hematopoietic differentiation through activation of unknown target genes. May be involved in the senescence of prostate epithelial cells. Involved in innate immune response by recognizing viral dsDNA in the cytosol and probably in the nucleus. After binding to viral DNA in the cytoplasm recruits TMEM173/STING and mediates the induction of IFN-beta. Has anti-inflammatory activity and inhibits the activation of the AIM2 inflammasome, probably via association with AIM2. Proposed to bind viral DNA in the nucleus, such as of Kaposi's sarcoma-associated herpesvirus, and to induce the formation of nuclear caspase-1-activating inflammasome formation via association with PYCARD. Inhibits replication of herpesviruses such as human cytomegalovirus (HCMV) probably by interfering with promoter recruitment of members of the Sp1 family of transcription factors. Necessary to activate the IRF3 signaling cascade during human herpes simplex virus 1 (HHV-1) infection and promotes the assembly of heterochromatin on herpesviral DNA and inhibition of viral immediate-early gene expression and replication. Involved in the MTA1-mediated epigenetic regulation of ESR1 expression in breast cancer. [Isoform IFI16-beta]: Isoform that specifically inhibits the AIM2 inflammasome. Binds double-stranded DNA (dsDNA) in the cytoplasm, impeding its detection by AIM2. Also prevents the interaction between AIM2 and PYCARD/ASC via its interaction with AIM2, thereby inhibiting assembly of the AIM2 inflammasome. This isoform also weakly induce production of type I interferon-beta (IFNB1) via its interaction with STING1.
Synonyms: IFNGIP1; PYHIN2
Tractability: PROTAC: UniProt records ubiquitination sites on it; ubiquitination databases record sites on it; its protein half-life has been measured.
Gene: Protein-coding gene on chromosome 1 (158,999,953 to 159,055,156, forward strand). Ensembl gene ENSG00000163565.
Subcellular location: Nucleus; Cytoplasm; Cytoplasm (Isoform IFI16-beta)
Subcellular location (Human Protein Atlas): Nucleoli; Nucleoplasm; Cytosol
Pathways (Reactome):
Immune System: IRF3-mediated induction of type I IFN; STING mediated induction of host immune responses
Gene Ontology:
Molecular function: double-stranded DNA binding; protein binding; RNA binding; transcription factor binding
Biological process: cellular response to glucose starvation; cellular response to ionizing radiation; defense response to virus; monocyte differentiation; negative regulation of DNA binding; negative regulation of DNA-templated transcription; negative regulation of gene expression, epigenetic; negative regulation of innate immune response; negative regulation of transcription by RNA polymerase II; negative regulation of viral genome replication; positive regulation of interleukin-1 beta production; positive regulation of transcription by RNA polymerase II; regulation of autophagy; regulation of inflammatory response; activation of innate immune response; cellular response to interferon-beta; myeloid cell differentiation; positive regulation of cytokine production
Cellular component: cytoplasm; cytosol; membrane; nuclear speck; nucleolus; nucleoplasm; nucleus
Genetic constraint (gnomAD): Loss-of-function variants: 33 observed, 47.13 expected, observed/expected ratio (o/e) 0.7, 90% interval 0.53 to 0.94. The upper end of that interval is the gene's LOEUF score, 0.94, which puts it in group 3 of 6, group 1 being the genes least tolerant of losing a copy. Missense variants: 693 observed, 724.79 expected, observed/expected ratio (o/e) 0.96, 90% interval 0.9 to 1.02. Synonymous variants: 248 observed, 257.63 expected, observed/expected ratio (o/e) 0.96, 90% interval 0.87 to 1.07.
Homologues: Orthologues: chimpanzee IFI16 (91% identical), macaque IFI16 (82% identical). Paralogues in human: PYHIN1 (41% identical), MNDA (26% identical), AIM2 (16% identical).
Diseases named in the same sentence as IFI16 in open-access papers:
IFI16 is named in the same sentence as 168 diseases in open-access papers, as found by Europe PMC text mining. Sharing a sentence is not in itself a finding about the gene and the disease. The quoted sentences say what the papers report.
viral infection (60 papers, 2012 to 2025). "Single and double proximity ligation microscopy, immunoprecipitation, EdU-genome labeled virus infection, and chromatin immunoprecipitation studies demonstrated that H2B is associated with IFI16 and BRCA1 in the nucleus in physiological conditions." (PMID 27764250, 2016). "This selectivity may underlie IFI16’s contribution to chronic immunopathology in persistent viral infections and their role in sepsis-related tissue damage." (PMID 40558557, 2025). "Deficiency of IFI16 leads to defective response to viral infection." (PMID 29691417, 2018). "This, combined with the fact that depletion of IFI16 leads to increased lentiviral replication, suggests that IFI16 has higher affinities for certain nucleic acid forms generated during viral infection." (PMID 40006739, 2025). "This versatile responsiveness positions IFI16 as a mediator between DNA damage, viral infections, and the initiation of inflammatory processes." (PMID 38693141, 2024). "IFI16’s ability to modulate viral infection responses demonstrates its dynamic regulatory role in host defense mechanisms." (PMID 38693141, 2024). "The intricate interplay between IFI16, DNA sensing, viral infections, and inflammatory pathways underscores its significance in maintaining immune homeostasis and shaping the host’s response to various threats." (PMID 38693141, 2024). "During viral infections, IFI16 recognizes viral DNA, subsequently inducing the expression of type I interferons (IFNs)." (PMID 38693141, 2024). "To address the role of each factor in the innate response against viral infection, we infected susceptible monocytic THP-1 cells WT or KO for STING, cGAS or IFI16 with NiV-eGFP or MeV-eGFP." (PMID 39283943, 2024). "IFI16 is a protein located in the nucleus and cytoplasm and acts as a DNA sensor during viral infections." (PMID 37998338, 2023). "As one of the DNA sensors, interferon (IFN)-γ inducible protein 16 (IFI16) play a major role in response to virus infections through activating the canonical STING/TBK-1/IRF3 signaling pathway." (PMID 37410794, 2023). "IFI16 inflammasome is a large signaling platform activated by IFI16 in response to viral infection, which also contains the adapter protein ASC (apoptosis-associated speck-like protein containing a caspase recruitment domain) and effector enzyme pro-caspase-1." (PMID 35906635, 2022). "For example, is IFI16 directed to specific genes, such as immediate early genes, to optimally suppress viral infection?" (PMID 35575489, 2022). "As the first discovered nuclear DNA sensor, investigations into the role of IFI16 during virus infections continue to lay the foundation for identifying and characterizing nuclear DNA sensors." (PMID 35575489, 2022). "IFI16 is an important double-stranded DNA (dsDNA) sensor that plays an essential role in innate immune response against viral infection." (PMID 36380368, 2022). "Studies have revealed that NLRP3, AIM2, and IFI16 sensors are pivotal for inflammasome activation in viral infections." (PMID 34595244, 2021). "While the relevance of PYHIN1 and MNDA in restricting viral infections in vivo remains to be determined, our results clearly demonstrate that they are about as effective as IFI16 in restricting HIV-1 in primary macrophages." (PMID 32760121, 2020). "PYHIN proteins, especially AIM2 and IFI16 are viral infection sensors and activate innate immune response in human cells." (PMID 33584656, 2020). "Concomitantly, it has been reported that IFI16 activates the inflammasome to suppress virus infection." (PMID 31423125, 2019). "BRCA1 forms a complex with IFI16 in the nucleus that is strengthened upon viral infection; this triggers translocation of IFI16 to the cytoplasm and inflammasome activation." (PMID 31827068, 2019). "Interferon-inducible protein 16 (IFI16), a newly discovered DNA sensor, plays an important role in the process of inflammation in viral infections." (PMID 29743020, 2018).
viral infection (continued). "Recent evidences show that IFI16 is involved in viral infection procedure and specifically serve as an inhibitor to viral infections." (PMID 29743020, 2018). "Taken together, IFI16 plays an important role in the process of immune response in viral infections." (PMID 29743020, 2018). "ATRX and IFI16 are both recruited to incoming viral DNA, but they do so independently and then restrict viral infection through independent pathways." (PMID 30465651, 2018). "Using human phorbol myristate acetate (PMA) treated THP1 cells and human monocyte-derived macrophages (MDMs) depleted of IFI16, we find that early interferon expression in the response to viral infections or DNA transfection requires IFI16." (PMID 28186168, 2017). "The translocation of IFI16 from cytoplasm to nucleus is regulated by the acetylation of nuclear IFI16 during viral infections." (PMID 28529930, 2017). "Our results showed the virus recognition receptors RIG-I, TLR3, and IFI16, which possibly be the mechanism that protects MSCs themselves against virus infection." (PMID 28105439, 2016). "This indicates that the IFI16 PY domain alone can increase the efficiency of CRY2 oligomerization, underscoring its function in assembly of IFI16 foci during viral infection." (PMID 27935834, 2016). "The finding that the nuclear DNA sensor IFI16 controls virus growth represents an important step forward in understanding the intrinsic mechanisms that drive viral infections sustained by DNA viruses such as Herpesviruses." (PMID 22291595, 2012). "Although less extensively studied in sepsis, other sensors such as AIM2 and IFI16—cytosolic and nuclear DNA detectors, respectively—have emerged as relevant contributors to the host inflammatory response, particularly in the context of viral infections." (PMID 40558557, 2025). "IFI16, a key player in DNA damage, viral infection, and inflammation, may become a central regulator of PANoptosis in heart diseases." (PMID 38693141, 2024). "The function of post-transcriptional regulation of IFI16 in viral infection is diverse." (PMID 37410794, 2023). "To gain a better understanding of the antiviral response nucleated by IFI16 during virus infection, we used a multiomics approach to map IFI16 binding to viral DNA and determine its impact on both viral genome accessibility and viral protein production during HSV-1 infection." (PMID 35575489, 2022). "Thus, IFI16 expression is required to tackle HCMV-mediated GLUT4 mRNA upregulation in the early stages of viral infection." (PMID 35420480, 2022). "Interferon gamma-inducible protein 16 (IFI16), known for playing roles in sensing viral infection and suppressing HSV gene expression in cultured cells was evaluated as the prototype interferon-related response in genital skin during and after HSV-2 reactivation." (PMID 34552595, 2021). "This study suggests that IFI16 cooperation with histone MTs is one of the critical mechanisms by which IFI16 regulates host innate immunity by sensing foreign DNA and inducing epigenetic modification during viral infection." (PMID 34299198, 2021). "Of note, new gene ontology data confirm ACE2 co-expression with immune response genes, in particular pro-inflammatory cytokines, chemokines and interferon γ-inducible protein 16 (IFI16), an innate immune sensor regulating the interferon response to viral infections by inflammasome activation." (PMID 34069409, 2021). "For example, the cellular compartments are guarded by various innate immune receptors to cope with viral infections and given the fact that many viruses replicate in the nucleus, then there must exist receptors for nuclear surveillance, as IFI16 is predominantly located in the nucleus." (PMID 33329609, 2020). "In addition to inducing IFN-I production as a DNA sensor, IFI16 induces the assembly of inflammasome complexes in response to DNA viruses, which is essential in immune protection against viral infections." (PMID 33505405, 2020).
viral infection (continued). "In addition to being tightly controlled transcriptionally during viral infection, IFI16 expression is precisely regulated during tumorigenesis." (PMID 33505405, 2020). "In contrast, p200 family protein IFI204/IFI16 is up-regulated during virus infection." (PMID 31603949, 2019). "Also, a significantly different immune response to virus infection (protein IFI16, interferons gamma and beta, dendritic cells, and receptor for natural killers) was revealed in the minor salivary glands of the study groups." (PMID 30723748, 2019). "The results indicated that intrinsic IFI16 responded to CHIKV infection indicating that it could play an important role in virus infection." (PMID 31423125, 2019). "Upon e.g. a viral infection IFI16 forms a transcriptional complex with other proteins." (PMID 30540779, 2018). "To better understand how IFI16 regulates the innate immune responses to viral infection, we utilized the CRISPR-Cas9 technology to generate knockout gene variants in human THP-1 cells, a monocytic cell line that adopts a macrophage-like phenotype on PMA differentiation." (PMID 28186168, 2017). "As we and others have reported IFI16-dependent induction of cytokines upon viral infection (2, –, 4, 6, 24), it is also possible that IFI16 may, in fact, function downstream of this canonical pathway (green pathway)." (PMID 27935834, 2016). "Additionally, autophagy genes IFI16, ZC3H12A, SQSTM1, WDR81, and PIK3R2 are associated with viral infection, including SARS-CoV-1 and were downregulated in this study when cells were treated with NIC." (PMID 37901834, 2023). "Thus, future investigations can determine if IFI16 enrichment at specific viral genomic loci represents a broad mechanism dictated by local genome accessibility and if active innate immunity prior to an acute viral infection or reactivation from latency influences IFI16 enrichment." (PMID 35575489, 2022). "During virus infection, viral nucleic acids are the main pathogen-associated molecular patterns (PAMPs) which can be detected by the cellular receptors such as retinoic acid-inducible gene I (RIG-I)-like receptors (RLRs) and interferon gamma-inducible protein 16 (IFI16) (DNA sensor)." (PMID 31888156, 2019). "To determine if the increased susceptibility to viral infection of the IL-21R KO mice could be due to an inherent altered expression of PRRs we measured mRNA levels of TLR2, TLR3, TLR9, MDA-5, AIM-2, DAI, RIG-I and IFI16." (PMID 24358128, 2013). "Other genes that were down-regulated with viral infection (GOLGA2, IFI16, WDR81, HK2, SQSTM1, ULK1) remained down-regulated with NIC treatment (with and without virus)." (PMID 37901834, 2023). "DNA sensors, including IFI16, DDX41, and cyclic GMP-AMP (cGAMP) synthase (cGAS), play a major role in response to virus infections through activating the canonical STING/TBK-1/IRF3 signaling pathway." (PMID 37410794, 2023). "Taken together, these results confirm that IFI16 acts as a transcriptional repressor of GLUT4, thereby reducing glucose consumption in HCMV-infected cells during the early stages of viral infection." (PMID 35420480, 2022). "In the nucleus, the binding of exogenous DNA by IFI16 leads to the formation of IFI16-ASC-procaspase-1 inflammasome and cytoplasmic translocation, resulting in the secretion of proinflammatory cytokine IL-1β to defend against viral infection." (PMID 35145495, 2021). "Previous studies have reported that IFI16 acts as a sensor for dsDNA in the nucleus, thereby also making it a valid sensor for HSV1 viral infection." (PMID 34203706, 2021). "IFI16 and RIG-I were demonstrated to be upregulated in the lung of flu virus-infected mice and IFI16 was shown to positively regulate the anti-viral RIG-I signaling pathway during virus infection." (PMID 36918931, 2023).
viral infection (continued). "Previous studies highlight IFI16 as a critical antiviral factor during virus infection, we speculated that the inhibition of TSN on PRRSV replication was related to the upregulation of IFI16 protein expression." (PMID 35906635, 2022). "The main pathways involved in virus infections include the NLRP3, IFI16, and AIM2 pathways." (PMID 34595244, 2021). "IFI16 interacts with SUV39H1 and GLP to generate the IFI16/SUV39H1/GLP complex, and the complex is recruited to the KSHV genome, leading to the methylation of H3K9 during viral infection and latency." (PMID 34299198, 2021). "A study showed that histone H2B interacted with IFI16 (gamma-interferon-inducible protein 16) and BRCA1 in the nucleus, and viral infections such as EBV, KSHV and HSV-1 induced the cytoplasmic distribution of H2B-IFI16 and H2B-BRCA1 complexes via Ran-GTP protein." (PMID 34868031, 2021). "In addition, it has been shown that TLR9 contributes to the production of type I IFNs to systemic viral infections, while cytosolic nucleic acid sensors including cGAS, IFI16 (mouse: Ifi204), RIG-I, and MDA5 mediate local immune responses to viral infections." (PMID 29963044, 2018). "Of the PRRs, the protein levels of AIM2 increased over time only with viral infection, whereas the levels of IFI16 and NLRP3 showed no remarkable change." (PMID 28369146, 2017). "DNA-PKcs, IFI16, Ku70, and Rad50 are DDR proteins involved in inducing the innate immune response to viral infection, and we hypothesised that PAXX may play a similar role." (PMID 29144403, 2017). "After detecting viral DNA or RNA, IFI16 induces the STING-dependent signal transduction through the TBK1-mediated IRF3 axis or IKKs-mediated NF-κB axis, which results in the production of IFN-I, proinflammatory cytokines, and chemokines against viral infection." (PMID 37410794, 2023). "In addition to cGAS, AIM2, IFI16, and DAI are the cytosolic DNA receptors, activation of which could induce innate immune response to virus infections." (PMID 33664729, 2020). "Other inflammasomes that have been reported during viral infections are AIM2 (absent in melanoma 2) and IFI16 (interferon-gamma-inducible protein 16)." (PMID 37515181, 2023).